KRAS (KRas proto-oncogene, GTPase)
Diseases named in the same sentence as KRAS in open-access papers (continued):
Sharing a sentence is not in itself a finding about the gene and the disease.
pancreatic cancer (continued). "Also, pancreatic cancer stem cells surviving to KRAS ablation rely on mitochondrial metabolism and show increased mROS levels." (PMID 32185131, 2020). "KRAS is a key oncogene in the development of lung and pancreatic cancer." (PMID 31874105, 2020). "KRAS (Kirsten rat sarcoma viral oncogene) mutations are present in 90% of pancreatic cancer patients, but an expression of only half of GRP78 prevents early pancreatic cancer development." (PMID 32850882, 2020). "MiR181ab1 expression is regulated by TGF-β in mutant-KRAS lung and pancreatic cancer cells." (PMID 31874105, 2020). "For example, using a specific gene signature for KRAS dependency, recently led to the identification and validation of decitabine as a potent inhibitor of growth in KRAS-dependent pancreatic cancer cells and patient-derived xenograft models, an approach that is now being translated to the clinic." (PMID 33115526, 2020). "Accumulating data from these analyses could facilitate the identification of new pancreatic cancer biomarker candidates other than KRAS." (PMID 32707720, 2020). "Indeed, KRAS is a candidate gene for early detection because it is considered a clonal oncogenic driver of pancreatic cancer and is present in ~95% of cases." (PMID 33317202, 2020). "Interestingly, results revealed a higher percentage of KRAS-wt status (67%), as opposite to canonical KRAS-mut pancreatic cancer, as also confirmed by a comprehensive systematic review coupled with a comparative analysis with large datasets." (PMID 33266496, 2020). "In KRAS-mutant Pa16C pancreatic cancer cells, while KRAS knockdown resulted in over 8,000 differentially methylated (DM) CpGs, treatment with the ERK1/2-selective inhibitor SCH772984 showed less than 40 DM CpGs, suggesting that ERK is not a broadly active driver of KRAS-associated DNA methylation." (PMID 32576853, 2020). "In the cfDNA analysis of this study, all paired FNA samples were derived from advanced pancreatic cancers with KRAS mutations; the detection rate of KRAS mutations in cfDNA by ddPCR was not very high (49%)." (PMID 32520974, 2020). "In addition, the CRISPR-Cas13a system was engineered for the targeted therapy of KRAS-G12D and KRAS-G12C mutants in pancreatic cancer." (PMID 32308773, 2020). "KRAS mutations are often seen with pancreatic cancer and non-small cell lung cancer, but not typically in breast cancers." (PMID 32370060, 2020). "In addition to the factors of KRAS alleles itself, NRF2 is also involved in the resistance mechanism in KRAS G12D mutant pancreatic cancer." (PMID 32404198, 2020). "In addition to these two cell lines, similar reduction of sphere formation upon ICMT knockdown was observed in other KRAS mutant pancreatic cancer cell lines, including AsPC1 and PANC1." (PMID 32561852, 2020). "First, we evaluated whether the expression of IL-6-family cytokines is modulated by oncogenic KRAS in pancreatic cancer." (PMID 31296870, 2019). "Oligonucleotide therapeutics can match this genomic profiling trend and target the molecules, including non-coding RNAs, which were not therapeutic targets previously, enabling the targeting of the KRAS gene, a critical trigger of pancreatic cancer progression." (PMID 31284594, 2019). "Because ERK is the most common effector downstream of KRAS, we determined whether KRAS upregulates PAI-1 via ERK in pancreatic cancer cells." (PMID 31695760, 2019).
pancreatic cancer (continued). "Liver cancer is associated with many types of mutations at a moderate abundance, compared to the domination of the pancreatic cancer landscape by KRAS. ctDNA analysis methods have also used gene panels in order to improve sensitivity and specificity in both HCC and PDAC." (PMID 31608239, 2019). "Targeted degradation of the KRAS oncoprotein through the ODC/AZ pathway at the post‐translational level may reflect a more effective future therapeutic strategy for pancreatic cancer patients." (PMID 30347501, 2019). "Oncogenic KRAS is an established driver of pancreatic cancer and several pathways that are known downstream effectors of KRAS signaling and play central roles in PDAC cancer cell growth and survival, were found to be marked by broad domains in domains common to all PDAC cells." (PMID 31815011, 2019). "EGFR inhibitors are less effective when the driver mutations are not specific to EGFR and instead harbored in KRAS, which is particularly important in pancreatic cancer because KRAS is mutated in approximately 95% of PDAC." (PMID 30921351, 2019). "ERK1/2 inhibitor can suppress growth of KRAS-mutant pancreatic tumors by targeting cancer cell." (PMID 31133044, 2019). "In KRAS-independent pancreatic tumours, the continued activation of MEK/ERK signalling by other mechanisms may still drive the MEK-FAM83A positive feed-back loop." (PMID 31527715, 2019). "In pancreatic intraepithelial neoplasia models of pancreatic cancer precursor lesions, KRAS signaling induced expression of IL-17 receptors on preneoplastic cells and infiltration by IL-17 secreting T-cells, both of which accelerated progression to a neoplastic state." (PMID 31681559, 2019). "Additionally, CIN can result in elevated mutant KRAS gene dosage in pancreatic cancer, which can drive higher expression of EMT genes and increase metastasis." (PMID 31681587, 2019). "Therefore, the present results indicate that KRAS/MEK/ERK activation can increase RAD51 expression in pancreatic cancer cells." (PMID 31889908, 2019). "Correlation of KRAS MAFs with clinical status of pancreatic cancer patients." (PMID 31850201, 2019). "To identify the differentially expressed KRAS mRNA in pancreatic tissues, we found that KRAS mRNA was significantly upregulated in human pancreatic tumor tissues (n = 45) compared to normal tissues (n = 45) (p = 3.26e−06) according to the GEO database (GEO: GSE28735)." (PMID 30654191, 2019). "Therefore, the authors designed oligonucleotides that mimic one of the G-quadruplexes formed by NHE (G4-decoys), and found that the decoy strategy inhibits KRAS in pancreatic cancer cells and reduces tumor growth in human pancreatic cancer xenograft mice." (PMID 31284594, 2019). "In this study, we show that a serum-stable, cell-penetrating, oligonucleotide-condensing, endosomolytic peptide-based NP system can deliver siRNA against KRAS to KRAS-driven cancers, reducing KRAS pathway expression, and slowing KRAS-driven pancreatic cancer growth in vivo." (PMID 31413817, 2019). "Accordingly, silencing KRAS is indicative of the inhibition of pancreatic cancer proliferation." (PMID 31284594, 2019). "It has been confirmed that KRAS depletion can inhibit pancreatic cancer cell progression." (PMID 30347501, 2019). "Moreover, CA125 serves as a prognostic marker for patients with pancreatic cancer, and mechanistic studies found that the KRAS/MYC axis drives the upregulation of MUC16/CA125." (PMID 31662990, 2019). "Next, we examined the functional roles of LIF in oncogenic KRAS-driven pancreatic cancers." (PMID 31296870, 2019). "In pancreatic cancer, inhibition of KRAS signaling induces extensive cancer cell death." (PMID 31324208, 2019).
pancreatic cancer (continued). "Importantly, we also found that C7 selectively inhibited the proliferation of pancreatic cancer cell lines, with KRAS-dependent lines displaying increased sensitivity compared with KRAS-independent lines." (PMID 31451509, 2019). "Thus, we sought to determine the roles and specific downstream signaling pathways of these IL6-family cytokine members in oncogenic KRAS-driven pancreatic cancers." (PMID 31296870, 2019). "However, in contrast to pancreatic cancers, where oncogenic KRAS mutations are found in 90% of the cases, a large population of CRC patients carry tumors that are wild type for KRAS." (PMID 30858928, 2019). "In pancreatic cancer, downregulation of KRAS and c-Myc may be markers of dormant pancreatic cancer cells." (PMID 30060755, 2018). "Conversely, distinct therapeutic options may be available for patients whose pancreatic tumours harbour wild-type KRAS." (PMID 30428574, 2018). "In addition, increased expression of oncogenic KRAS was observed in MUC13-expressing cells that is known to maintain pancreatic tumors through regulation of anabolic glucose metabolism." (PMID 29467405, 2018). "Although about 90% of pancreatic cancers harbor activated driver oncogenic KRAS, effective molecular targeted agent against KRAS mutation has not been developed until now." (PMID 30419860, 2018). "Moreover, Spiclomazine-treated pancreatic cancer cells exhibited cell cycle arrest, suggesting a contribution of inactivating KRas oncogene activation mechanism to the cell cycle distribution." (PMID 29467941, 2018). "The engineered exosomes (known as iExosomes) target oncogenic KRAS with enhanced efficacy probably due to that CD47 on exosomes surface contributed to the evasion from immune clearance in the circulation, and KRAS-stimulated macropinocytosis increased pancreatic cancer cells uptake of iExosomes." (PMID 29415727, 2018). "KRAS-driven pancreatic cancer cells bypass the oxidative phase of the pentose phosphate pathway." (PMID 30631752, 2018). "Obese mice with KRAS (KC) mutation in the pancreas fed with high-fat calorie diet (HFCD) exhibit severe deficiencies in the NK cell expansion and function at the pre-neoplastic stage of pancreatic cancer." (PMID 29977235, 2018). "Furthermore, PIP5K1A depletion specifically reduces oncogenic KRAS signaling and proliferation, and sensitizes pancreatic cancer cell lines to a MAPK inhibitor." (PMID 30194290, 2018). "Recent work showed that plasmid delivery and electroporation could be used to initiate KRAS-driven pancreatic cancer in the adult mouse and, similar to our findings, can be complemented with CRISPR-Cas9-mediated genome editing." (PMID 30061297, 2018). "In this study, genetically modified extracellular vesicles (referred to as iExosomes) were able to transport small RNA molecules specifically targeting the mutant KRAS gene, leading to alleviation of murine pancreatic cancer and increasing overall survival rate." (PMID 29850495, 2018). "Moreover, in pancreatic cancer, KRAS activates Src in a pseudopodium-enriched atypical kinase 1 (PEAK1)-dependent manner or directly cooperates with Src, leading to metastatic tumor growth, therapy resistance, and accelerated tumorigenesis." (PMID 29455661, 2018). "Therefore, investigating strategies for effective inhibition of KRAS signaling is critically important in pancreatic cancer research." (PMID 29435178, 2018). "Moreover, mouse models of KRAS-driven pancreatic cancer were shown to be partially dependent on SMYD2 and indicate that genotoxic agents are more effective in the absence of SMYD2 activity." (PMID 29856759, 2018). "Further, anti-tumor effect of triptolide was verified through PDCs from metastatic pancreatic cancer patients with and without KRAS mutation." (PMID 30419860, 2018).
pancreatic cancer (continued). "In general, the mutational frequency data combined with the observation from the simulations suggest that at least in the pancreatic cancer, where a KRAS mutation is a key initiator, a major shift in KRAS dynamics is not tolerated." (PMID 30199525, 2018). "The authors showed that the correction model did not hinder the identification of known cancer-specific dependencies in amplified regions as they were able to identify the KRAS dependence of a KRAS-mutant pancreatic cancer cell line in which the gene was amplified." (PMID 29561791, 2018). "Conversely, in KRAS-mut contexts (MiaPaCa2 pancreatic cancer; A549 and A-427 NSCLC), EGFR family activation was dispensable for dabrafenib-induced paradoxical ERK activation, as the addition of lapatinib to dabrafenib had no appreciable effect on ERK activation." (PMID 29986755, 2018). "It is well known that mutations in KRAS are almost omnipresent in pancreatic cancer development and progression, and only our EXAT method could find KRAS as a significant gene." (PMID 29697368, 2018). "Sensitivity and specificity were respectively defined as the proportion of KRAS mutation-positive samples among samples from patients of pancreatic cancer and the proportion of KRAS mutation-negative samples among samples from the control population." (PMID 29451897, 2018). "A recent study has demonstrated that lncRNA NUTF2P3-001 acts as a ceRNA to communicate with KRAS by competitively binding to hsa-mir-3923, and the up-regulation of NUTF2P3-001 reverses the suppressive effect of hsa-mir-3923 on KRAS, leading to the proliferation and invasion of pancreatic cancer." (PMID 30261893, 2018). "Notably, signaling downstream of mutant KRAS in pancreatic cancers leads to mitochondrial fragmentation and increased activation of Drp1, processes that are required for KRAS-driven tumor growth in vivo." (PMID 29700304, 2018). "Another group used antisense oligonucleotides to demonstrate that KSR1 knockdown could reduce growth of KRAS-dependent human pancreatic carcinoma xenografts in nude mice." (PMID 29596465, 2018). "Pancreatic cancer cells may develop resistance to KRAS inhibitors due to activation of compensatory pathways." (PMID 29061961, 2017). "KRAS cooperates with Gli1 to induce pancreatic cancer in a mouse model." (PMID 29163356, 2017). "We applied a well-established network biology approach (master regulator analysis) to combine a transcriptional signature for oncogenic KRAS derived from a murine isogenic cell line with a coexpression network derived by integrating 560 human pancreatic cancer cases across seven studies." (PMID 28141826, 2017). "It is of interest to note that not all pancreatic cancers have a mutation of either KRAS or BRAF: thus, about 5% of these tumors do not possess an RAS mutation." (PMID 29156578, 2017). "Furthermore, BAY ACC002 was active in both mutant KRAS (Capan-2, DanG) and wild-type KRAS (BxPC-3) pancreatic cancer cells." (PMID 27750213, 2017). "Finally, in disease animal models, conditional deletion of USP9X cooperates with oncogenic KRAS to induce pancreatic cancer development." (PMID 29156578, 2017). "Additional evidence that MYC dysregulates glutamine metabolism was provided by a recent study that found elevation of the glutamine synthetase (Glul) enzyme and glutamine abundance in a transgenic mouse model of dual MYC and KRAS-driven pancreatic cancer, compared to tumors driven by KRAS alone." (PMID 28443280, 2017). "In the current study, we apply systems biology approaches to enable a better understanding of the dynamics of the distinct metabolic alterations in KRAS-mediated pancreatic cancer, with the goal of impeding early cell proliferation by identifying the optimal metabolic enzymes to target." (PMID 28446878, 2017).
pancreatic cancer (continued). "The effects of sulforaphane (present in broccoli, brussel sprouts, cabbage and other cruciferous vegetables), quercetin (a flavonol found in many fruits, grains, leaves and vegetables) and catechins have been examined on let-7 miR induction and KRAS suppression in pancreatic cancer cells." (PMID 28611316, 2017). "In addition, we analyzed the expression of the c-MYC, HMGA2 and KRAS mRNAs in the pancreatic cancer samples from the GSE data sets." (PMID 28947981, 2017). "Intriguingly, although KRAS mutations are reported for 99% of PanIN-1s37, no more than 95% of pancreatic cancers have a KRAS or BRAF mutation, supporting the notion that a KRAS mutation is not strictly required for the development of pancreatic cancer." (PMID 28008139, 2017). "Indeed, murine pancreatic cancers with activated KRAS (e.g. KRASG12D and KRASG12V) exhibit oncogene addiction, whereby suppression of KRAS activity induces cell death in advanced tumors and regression of early PanINs." (PMID 28415794, 2017). "KRAS is the most commonly activated oncogene in pancreatic cancer." (PMID 28435405, 2017). "Given the upregulation of these miRNAs in human pancreatic cancers and their validated role as oncogenes in a variety of contexts, we hypothesized that they contribute to KRAS-induced pancreatic tumorigenesis." (PMID 28415794, 2017). "KRAS mutations are the most frequently acquired genetic alteration in PDAC, and detecting this mutation from pancreatic tissue has been helpful in the diagnosis of pancreatic cancer." (PMID 27974679, 2017). "Moreover, KRAS is a critical regulator for the maintenance of mesenchymal phenotypes and metastatic ability in skin, breast, colon and pancreatic cancers." (PMID 27901498, 2017). "Thus, Eser and coworkers have provided evidence that PI3K, as well as 3-phosphoinositide-dependent kinase 1 (PDK1) are activated in tumor pancreatic neoplasia (including preneoplastic lesions), as well as in KRAS-driven murine pancreatic cancer." (PMID 29156578, 2017). "In addition, we used this library to compare cell essential genes in HT29 and a KRAS-mutant pancreatic cancer line MIAPACA2." (PMID 28534478, 2017). "Therefore, it seemed particularly interesting to evaluate a possible cooperation between KRAS mutation and SMAD4 loss in favoring the progression of pancreatic cancer." (PMID 29156578, 2017). "Interestingly, recent studies indicate that oncogenic KRAS forms a critical axis with the JNK pathway that can regulate pancreatic tumor formation." (PMID 26840266, 2016). "It has been described in pancreatic cancer and studies suggest that MSI may be associated with KRAS mutations." (PMID 26884312, 2016). "Moreover, miR-96 and miR-217 were found as inhibitors in the development of pancreatic cancer by prohibiting KRAS expression." (PMID 26755660, 2016). "The KRAS codon 12 mutation was previously reported as a negative prognostic factor for unresectable pancreatic cancer." (PMID 27077911, 2016). "In pancreatic cancer, KRAS is considered the earliest oncogenic event." (PMID 27634878, 2016). "In this report, in order to detect KRAS point mutations in pancreatic cancer cells we developed a novel, non-PCR molecular method, PNA-LNA mediated LAMP, which takes advantage of both LAMP technology and high sequence specific artificial nucleic acids." (PMID 26999437, 2016). "In addition, we demonstrated that chloroquine, a classical inhibitor of autophagic flux, can reverse the effect of VMP1 overexpression on pancreatic cancer induced by the KRAS oncogene in a preclinical trial using our mouse model." (PMID 27833900, 2016).